CRP (C-reactive protein)
Diseases named in the same sentence as CRP in open-access papers (continued):
Sharing a sentence is not in itself a finding about the gene and the disease.
bacterial infection (continued). "We observed that factors such as a longer duration of fever or physician suspicion of bacterial infection were associated with the performance of CBC, CRP, and even urinalysis tests in patients with URTI symptoms." (PMID 38786268, 2024). "Patients with procalcitonin testing were older, had more comorbidities, higher neutrophil count, higher C reactive protein, and higher prevalence of bacterial infections, and a higher proportion required intensive care." (PMID 38243171, 2024). "Complete blood count (CBC) and C-reactive protein (CRP) determinations in blood samples are considered the most effective biomarkers for inflammatory diseases such as bacterial infections." (PMID 39143348, 2024). "Serum IL-6 is markedly increased in response to bacterial infection, activating monocytes and macrophages and inducing the release of CRP and PCT." (PMID 38504206, 2024). "This study provides proof of concept that OPG increases differentially in bacterial infections, although with a lower sensitivity than CRP." (PMID 38509997, 2024). "It is described as an acute phase pro-inflammatory cytokine, which increases its blood level within the first 6 h, earlier than CRP, during bacterial infections." (PMID 38254697, 2024). "Rapid point-of-care testing (POCT) methods for CRP have emerged as essential tools in clinical settings, particularly for managing bacterial infections at the bedside." (PMID 39337259, 2024). "Existing biomarkers like white blood cell count, C-reactive protein, procalcitonin, and presepsin have limitations in their ability to distinguish (serious) bacterial infections from other etiologies of fever." (PMID 38539311, 2024). "It clearly distinguishes viral and bacterial infections, rises more rapidly when compared to CRP levels, and peaks within a very short time." (PMID 39006695, 2024). "Lung viral or bacterial infections and substantial colonization aggravate airway inflammation, leading to an increase in white blood cell count, procalcitonin, and C-reactive protein." (PMID 39705475, 2024). "Value of WBC, CRP, NLR, LWR, PLT and WBC × CRP for differential diagnosis in patients with influenza B and bacterial infection." (PMID 38306568, 2024). "We considered those in the subgroups with peak CRP levels on day 1 or day 2 (52.1% episodes) to have a “normal” response, also representing appropriate antimicrobial treatment in those with bacterial infection." (PMID 38599549, 2024). "PCT demonstrated the highest predictive value for bacterial infections (AUC = 0.874), followed by CRP (AUC = 0.855) and NLR (AUC = 0.792) (p < 0.0001)." (PMID 39296886, 2024). "Despite the low CRP level measured (<20 mg/L), GP often preferred to prescribe antibiotics, although serious bacterial infections would be unlikely for these patients." (PMID 39335040, 2024). "It has also been reported that PCT is a more accurate marker for differential diagnosis of bacterial infection compared with CRP." (PMID 38577990, 2024). "Lower CRP concentrations at admission appear to be related to fatigue during acute viral and bacterial infection." (PMID 38930481, 2024). "C-reactive protein (CRP) measurement can help identify those who are more likely to have a bacterial infection and therefore need antibiotic treatment." (PMID 38241274, 2024). "CRP levels tend to rise with bacterial infections and then decline exponentially within 18 to 20 h once the underlying stimulus diminishes." (PMID 38373918, 2024). "Rapid point-of-care testing (POCT) methods have emerged for CRP application in clinical settings, particularly for managing bacterial infections at the bedside." (PMID 39337259, 2024). "In contrast to PCT, which is highly selective for bacterial infections, CRP is an acute-phase protein that reflects systemic inflammation." (PMID 39469363, 2024).
bacterial infection (continued). "Laboratory measurements typically had 12–14% missing data, except for serum procalcitonin (PCT), a marker for bacterial infections, with 24.5% missing, and C-reactive protein (CRP), a marker of inflammation, with 16.8% missing." (PMID 39266748, 2024). "Our CBC test analysis demonstrated that elevated WBC count and CRP in the untreated positive control group indicate active bacterial infection." (PMID 38911027, 2024). "Patients with procalcitonin testing were older, had more comorbidities, higher neutrophil and C reactive protein, and higher prevalence of documented bacterial infections." (PMID 38243171, 2024). "CRP is a marker of inflammation that increases during bacterial infection in response to cytokines IL-1 and IL-6 and has a stable decay rate." (PMID 38509997, 2024). "Studies initially demonstrated PCT’s superiority over CRP in bacterial infection diagnosis, with recent research suggesting its ability to predict blood culture results in critically ill patients." (PMID 39768616, 2024). "Circulating CRP and IL-6 are established biomarkers for bacterial infections but have limited value for characterizing disease severity or for making specific prognoses for individual cases." (PMID 36980300, 2023). "Antibiotics were administered in cases of concomitant signs and symptoms of bacterial infection, especially in the presence of significantly elevated inflammatory markers such as CRP and PCT or microbiological confirmation." (PMID 37376507, 2023). "Concentrations of CRP start to increase in serum approximately 6 to 12 hours with maximum concentration after 24 to 72 hours after the onset of a bacterial infection." (PMID 37904468, 2023). "CRP is a marker widely used in clinical pediatric practice to help us evaluate inflammation and possible bacterial infection." (PMID 37904468, 2023). "Studies have indicated that procalcitonin values of 1 μg/L or higher show better specificity, sensitivity, and predictive value for distinguishing viral from bacterial infections in children compared to CRP, interleukin 6, or interferon-alpha." (PMID 37600437, 2023). "For instance, there is little data on CRP, other than to differentiate viral and bacterial infections in primary healthcare." (PMID 37612636, 2023). "CRP is a pattern recognition molecule that plays an important role in defense against bacterial infections." (PMID 36879818, 2023). "Previous studies confirm the value of calprotectin in the identification of bacterial infections, with better sensitivity and specificity than CRP and PCT." (PMID 37626653, 2023). "Plasma C-reactive protein (CRP) rises well above normal when there is a bacterial infection, and thus plasma CRP level can be used to identify bacterial RTI." (PMID 36509332, 2023). "This has been due to its reported accuracy and superiority over CRP in determining the diagnosis of bacterial infections in hospitalised patients." (PMID 37107071, 2023). "Many potential biomarkers have been evaluated to enable the prediction of bacterial infection in febrile patients, with C reactive protein (CRP) showing a lot of promise." (PMID 37478118, 2023). "In one study, CRP values > 25 mg/dL within a six-biomarker combination were able to diagnose severe bacterial infections in children with the highest sensitivity." (PMID 39554800, 2023). "Independently of bacterial infection, CRP has been shown to accurately predict Plasmodium parasitemia in studies in Angola and Ghana." (PMID 37478118, 2023). "The patient was suspected of having an incipient acute mononucleosis and CRP examination from capillary blood was performed to distinguish between viral and bacterial infection." (PMID 37904468, 2023). "Serum c-reactive protein, which is a biomarker of bacterial infection in swine, was present in the piglets fed the E. coli-contaminated fishmeal, but the level was same as that of the control group when the fishmeal was treated with γ-ray irradiation." (PMID 37958171, 2023).
bacterial infection (continued). "For example, C-reactive protein (CRP) testing provides real-time assessment of likelihood of bacterial infection, reducing antibiotic prescribing in primary care." (PMID 37612636, 2023). "The CRP levels were normal (3.4 ± 9.7 mg/L) in the majority of patients, and only 9 patients had a significant increase in CRP levels (≥10 mg/L), suggesting the possibility of bacterial infection due to elevated levels of CRP." (PMID 37565246, 2023). "Pooled specificity was calculated to be 0.90 (95% CI 0.85–0.93) for PCT and 0.56 (95% CI 0.25–0.83) for CRP to identify bacterial infections in a meta-analysis." (PMID 37296721, 2023). "The cytokines TNF-α, IL-1α and IL-6 promote the synthesis of acute phase proteins such as C-reactive protein, by hepatocytes, the concentration of which is significantly increased during bacterial infection or tissue damage." (PMID 36937280, 2023). "With an AUC of 0.62 (95% CI 0.48–0.76), PCT demonstrated similar performance to ferritin, WBC, and CRP in predicting bacterial infection." (PMID 36752185, 2023). "The acute phase reactant C-reactive protein (CRP), secreted by the liver in response to cytokines such as interleukin 6 (IL-6), rises within 6–8 h after the onset of acute viral or bacterial infections, aiding in innate immune responses." (PMID 38003780, 2023). "It was previously discussed that various inflammatory disorders can have raised concentrations, and some bacterial infections can occur in parallel with an up to 1000-fold increase in CRP levels." (PMID 37873776, 2023). "Labscore, ImmunoXpert, and CRP attained the highest AUC values for the detection of bacterial infection, respectively 0.854 (0.804–0.905), 0.827 (0.764–0.890), and 0.807 (0.744–0.869)." (PMID 37956117, 2023). "When bacterial infections were analyzed separately, length of hospital stay and C-reactive protein were statistically significant in the multivariate analysis." (PMID 37484846, 2023). "In bacterial infections, monitoring C-reactive protein or procalcitonine in blood can be useful to support the decision of early stop of antibiotics." (PMID 36847873, 2023). "Contrary to the serum concentration of CRP, local bacterial infections, and viral and other non-bacterial infections result in a lower increase in the serum concentration of PCT." (PMID 36834338, 2023). "Based on first-level laboratory work-up, children with neutrophilia and higher values of CRP more often received empiric antibiotic therapy, also considering possible invasive bacterial infection." (PMID 38002879, 2023). "The Labscore and the ImmunoXpert show better diagnostic performances for safely detecting bacterial infection in children with FWS, compared to individual biomarkers such as CRP, PCT, WBC or ANC." (PMID 37956117, 2023). "It is a relatively new biomarker that outperforms the traditional biomarkers, such as C-reactive protein and leukocyte count, when used for the diagnosis of bacterial infection and for the monitoring of antibiotic therapy." (PMID 38138232, 2023). "Another limitation is that this study did not evaluate the serum PCT level, which is a more specific biomarker of bacterial infection than WBC count or CRP level." (PMID 37435240, 2023). "Particularly, C-reactive protein POCT can rapidly and efficiently assist physicians in the identification of bacterial infections, reducing the diagnostic uncertainty and unnecessary antibiotic prescriptions for ARIs." (PMID 36830207, 2023). "Several studies therefore supported the combination of MxA with a biomarker specific for bacterial infections, such as CRP." (PMID 36737561, 2023). "In our study, although 5 children in the severe group had a bacterial infection, we tested CRP within 24 hours of admission, and it usually peaks at 24-48 hours." (PMID 37249974, 2023). "Bacterial infections frequently provide a strong stimulus for a systemic acute phase response manifested by the increased plasma proteins production including C-reactive protein (CRP)." (PMID 38077410, 2023).
bacterial infection (continued). "Levels of CRP in combination with PCT is a reliable index for the detection of bacterial infection in these patients." (PMID 37296721, 2023). "Procalcitonin (PCT) and C-reactive protein (CRP) are considered markers used in clinical practice to differentiate bacterial infections from autoimmune origin." (PMID 37064073, 2023). "Main presenting features, the number of HAdV copies, the role of CRP for differential diagnosis with bacterial infection, and the assessment of the need for hospitalization and antibiotic therapy were analyzed in a consecutive series of 100 cases." (PMID 38002879, 2023). "This also indicates that CRP cannot be utilized as a reliable marker of severe bacterial infection in these patients, and in contrast to the GiACTA trial, a multicentre study in patients with GCA given tocilizumab reported far more serious infections (11.9%)." (PMID 38020122, 2023). "CRP has been widely used clinically for aiding the diagnosis of bacterial infection by combining with WBC and neutrophil accounts in blood routine test." (PMID 36806964, 2023). "Studies have shown that CRP levels are higher during exacerbations of COPD compared to baseline levels, particularly in patients with COPD exacerbations caused by bacterial infections." (PMID 37400821, 2023). "The WBC, procalcitonin (PCT), and C-reactive protein (CRP) levels are frequently used biomarkers that can differentiate viral and bacterial infections." (PMID 37144031, 2023). "At the same time, CRP levels, together with pro-calcitonin levels, can help to detect superimposed bacterial infections earlier, improving the appropriateness of antibiotic therapy." (PMID 37760914, 2023). "An old study has shown various serum CRP levels in acute otitis media cases, but high values (>20 mg/L) were observed in those with bacterial infection." (PMID 37873776, 2023). "On the other hand, there are documented cases where children's CRP levels remain low despite serious bacterial infections." (PMID 37900677, 2023). "Procalcitonin is a peptide, produced by monocytes and hepatocytes in response to systemic inflammation and, according to some studies, appears to be more sensitive than CRP in bacterial infections." (PMID 37755410, 2023). "In general, PCT and CRP show poor sensitivity but adequate specificity in the recognition of bacterial infection in patients with CRI." (PMID 37296721, 2023). "Shed P2X7R did not significantly correlate with CRP but, very interestingly, showed a strong positive correlation with PCT (r = 0.355; p = 0.009), an index of bacterial infection more specific than CRP." (PMID 37215142, 2023). "In case of worsening of the clinical conditions, clinicians should consider repeating CRP testing, taking into account the possibility of a secondary bacterial infection." (PMID 37900677, 2023). "Studies have added that the advantages of WBC count over CRP are that its typical level increases mostly in bacterial infection, and its normal level is rapidly re-established after antibiotic treatment." (PMID 36329535, 2022). "In the case of confirmed non-bacterial infections, positive CRP levels were found in 85.1% (63/74) of the febrile children." (PMID 36536340, 2022). "The single and combined positive rates of SAA, PCT and CRP in the bacterial infection group were the highest, which were 72.00%, 83.00%, 62.00% and 89.00%, respectively." (PMID 35775463, 2022). "Based on a meta-analysis, PCT has been found to be a more sensitive and specific biomarker compared to CRP in distinguishing bacterial from non-bacterial infections." (PMID 36295492, 2022). "The most commonly used inflammatory markers such as white blood cell count (WBC), C-reactive protein (CRP), and procalcitonin (PCT) aid in identifying children at risk for bacterial infection, though their sensitivity and predictive ability are limited." (PMID 35359908, 2022).
bacterial infection (continued). "Compared to C-reactive protein, the biomarker, procalcitonin, shows a more vital and faster modulation for the severity of bacterial infection." (PMID 35547462, 2022). "Standard blood biomarkers such as leukocytes, neutrophils, and CRP have been evaluated, and they are the most commonly used biomarkers to date in differentiating viral versus bacterial infections." (PMID 36362702, 2022). "It should be noted that in the group of patients presenting with low CRP and a bacterial infection, there was a significant difference between the eCRPv and the CRPv." (PMID 35897672, 2022). "The serum CRP level of the patients with IFI was significantly higher than that of those with bacterial infection (100.57 [64.00–157.83] versus 40.04 [11.90–74.84] mg/L, median [IQR], p < 0.001)." (PMID 35740137, 2022). "Forty-three biomarkers were investigated, of which 6 (CRP, PCT, IL-8, IL-6, IL-10, and TNFα) were significantly associated with bacterial infection at admission, studied in multiple studies, and provided predictive data." (PMID 35372147, 2022). "The short pentraxin CRP has traditionally been utilized as an acute-phase protein to indicate bacterial infection, but it is limited by a delayed response." (PMID 35704081, 2022). "The analysis of groups of patients with iso-CRP (i.e., with a similar range of CRP concentration) indicates that in high values of CRP concentration most of the patients have a bacterial infection." (PMID 36477474, 2022). "In total, the analysis comprised 1444 patients tested with PCT and 1279 patients tested with CRP, of which 430 (29.8%) and 392 (30.6%) patients were experiencing bacterial infections, respectively." (PMID 35164633, 2022). "C-reactive protein (CRP) is an important part of the immune system’s reaction to various pathological impulses such as bacterial infections, systemic inflammation, and internal organ failures." (PMID 35624645, 2022). "Due to bacterial infection, CRP levels rise within the first 6 to 8 h in response to several inflammatory stimuli." (PMID 35453219, 2022). "We explored the possibility of using the kinetics of CRP (eCRPv) as a possible aid to discriminate between a viral and a bacterial infection." (PMID 36477474, 2022). "In our study, the blood MxA/CRP ratio yielded better sum of sensitivity and specificity than MxA measurement alone in differentiating between viral and bacterial infections." (PMID 35080443, 2022). "Transgenic or passively administered human CRP was protective against lethal bacterial infection in transgenic mice." (PMID 36275680, 2022). "CRP count is generally elevated in bacterial infections and often helps physicians to differentiate between viral and bacterial infections and thus helps in prescribing required antibiotics." (PMID 36290008, 2022). "The optimal CRP cut-off used in the diagnosis of bacterial infections in NICU patients varies by the time from symptom onset." (PMID 36517750, 2022). "On the other hand, the efficacy of bacterial infection diagnosis based on CRP followed by antibiotics prescription is positively accepted by physicians, and the reliability has been verified in several studies." (PMID 35624645, 2022). "The area under the ROC curve for CRP velocity to diagnose bacterial infection in NICU patients was 0.77 (95% CI:0.66–0.88)." (PMID 36517750, 2022). "The functions of rOn-CRP against bacterial infection were further determined by detecting numerous immune-related genes via qRT-PCR." (PMID 36009776, 2022). "In conclusion, the optimal cut-off for CRP to diagnose bacterial infections in NICU patients varies by the time from symptom onset." (PMID 36517750, 2022). "We have previously shown that the optimal cut-off CRP value for the diagnosis of bacterial infection, among children presenting to the emergency department (ED), changed with time from fever onset." (PMID 36517750, 2022).